NET1 (neuroepithelial cell transforming 1)
Diseases named in the same sentence as NET1 in open-access papers (continued):
Sharing a sentence is not in itself a finding about the gene and the disease.
lung carcinoma (5 papers, 2020 to 2025). "We emphasize to analyze the effect and function of miR-22 as well as its underlying potential target NET1 in lung cancer." (PMID 32420320, 2020). "Nevertheless, the roles and underlying mechanisms of NET1 in lung cancer are still unexplored." (PMID 33955315, 2021). "Previous studies show that the miR-340-5p/NET1 axis-dependent effect of baicalin can suppress lung cancer progression." (PMID 40561678, 2025). "Luciferase activity indicated NET1-Wt was reduced by miR-340-5p mimics, whereas miR-340-5p overexpression dramatically reduced NET1 expression in lung cancer cells." (PMID 33955315, 2021). "Quantitative RT-PCR showed miR-340-5p mimics significantly decreased NET1 expression in lung cancer cells." (PMID 33955315, 2021). "In summary, baicalin suppressed lung cancer progression by affecting the miR-340-5p/NET1 axis, suggesting a potential therapeutic target for the treatment of lung cancer." (PMID 33955315, 2021). "Our results showed that the anti-tumor effects of Baicalin on lung cancer growth characteristics were through modulation the miR-340-5p/neuroepithelial transforming gene 1 (NET1) partnership." (PMID 33955315, 2021). "Next, functional rescue assays showed that overexpression NET1 reversed the suppressive effects of Baicalin on lung cancer cells proliferative, and invasive capabilities." (PMID 33955315, 2021). "Rescue assays revealed NET1 overexpression reversed the effects induced by baicalin on lung cancer cells phenotypes." (PMID 33955315, 2021). "Further study will be necessary to focus on the in vivo roles of miR-22 together with NET1 that appear to play a pivotal role in lung cancer." (PMID 32420320, 2020). "We then detected NET1 protein levels in lung cancer and adjacent normal tissues, as well as in NSCLC cell lines by western blot." (PMID 32420320, 2020). "Abnormal expression of neuroepithelial cell transforming gene 1 (NET1) has been authenticated in many human cancers, including lung cancer." (PMID 32420320, 2020). "Thus, baicalin elicited antitumor activities by affecting the miR-340-5p/NET1 axis, suggesting a new approach to lung cancer clinical management." (PMID 33955315, 2021). "Furthermore, neuroepithelial cell transforming 1 (NET1) functioned as a miR-340-5p target, and acted in a baicalin-dependent manner to regulate lung cancer progression." (PMID 33955315, 2021). "Although the neuroepithelial cell transforming gene 1 (NET1) is identified as an oncogene in many human cancers, including lung cancer, miRNAs that could directly modulate NET1 in the regulation of NSCLC cancer are poorly elucidated." (PMID 32420320, 2020). "As predicted by the Targetscan and miRDB database, NET1 was a target gene of miR-22 in lung cancer." (PMID 32420320, 2020). "However, it is still unknown whether and how NET1 was modulated by miRs in lung cancer." (PMID 32420320, 2020).
acute lymphoblastic leukemia (4 papers, 2020 to 2025). Leukemia with an acute onset, characterized by the presence of lymphoblasts in the bone marrow and the peripheral blood. "CircRNA circ0000745 competitively inhibits miR-494-3p to upregulate neuroepithelial cell transforming 1 (NET1), a guanine nucleotide exchange factor of RhoA, to suppress ferroptosis in acute lymphoblastic leukemia cells." (PMID 37686142, 2023). "Additionally, NET1 increases cell migration in both ER-positive and ER-negative cells and enhances proliferation and chemoresistance and was regulated by miR-206 in B-acute lymphoblastic leukemia (B-ALL) cells." (PMID 32420320, 2020).
cervical cancer (3 papers, 2013 to 2020). A primary or metastatic malignant neoplasm involving the cervix. "It has been seen that Net1 is overexpressed in cervical cancer tissues, correlating with microvessel density and aggressive clinical behavior (lymph node metastasis, vascular invasion, etc.)." (PMID 32455616, 2020). "They found that NET-1 gene was expressed in CIN III, cervical squamous cell carcinoma, all undifferentiated cervical carcinoma and adenocarcinoma, indicating that NET-1 gene may be a marker for cervical cancer." (PMID 24196235, 2014). "Net1 siRNA decreased the proliferation, migration and angiogenesis capacity of SiHa cells, achieving a reduction in tumor growth and microvessel density of cervical cancer in vivo, maybe through VEGF downregulation." (PMID 32455616, 2020).
glioma (3 papers, 2021 to 2025). A benign or malignant brain and spinal cord tumor that arises from glial cells (astrocytes, oligodendrocytes, ependymal cells). "Net-1 dysregulation has been implicated in tumor proliferation and resistance to apoptosis in various cancers, including glioma." (PMID 39719558, 2024). "Subsequent treatment with TMZ and γ-radiation further increased p38-MAPK activity through the decreased expression of Rho-A/Net-1, resulting in a significant reduction in glioma cell migration and invasion." (PMID 39719558, 2024). "Among the most strongly decreased candidates, we observed proteins related to DNA repair (FANCA, USP38, NET1), autophagy (BCAS3), cancer cell migration and/or invasion (RASSF2, KMO, BCAS3), as well as proteins that can be generally considered as pro-tumorigenic, particularly in glioma (KMO, BCAS3)." (PMID 39833546, 2025).
bladder cancer (2 papers, 2020 to 2021). "For instance, downregulation of NET1 targeted by miR-22 has been reported to promote chemoresistance, and miR-22 acts as a novel prognostic biomarker in bladder cancer patients." (PMID 32420320, 2020).
breast tumors (2 papers, 2011 to 2018).
colorectal cancer (2 papers, 2011 to 2017). A primary or metastatic malignant neoplasm that affects the colon or rectum. "NET1 promotes endothelial cell nitric oxide production and cell growth and migration in vitro via the receptor deleted in colorectal cancer (DCC)." (PMID 28824923, 2017).
gastric adenocarcinoma (2 papers, 2011 to 2013). "NET1 has been shown to be functionally important as a mediator of invasion and metastasis in gastric adenocarcinoma and is prognostically significant in other epithelial cancers." (PMID 23945136, 2013). "Neuroepithelial Transforming Gene 1 (NET1) is a well characterised oncoprotein and a proven marker of an aggressive phenotype in a number of cancers, including gastric adenocarcinoma." (PMID 23945136, 2013). "In order to further examine the role of NET1 in the disease setting, we created a unique Human Caucasian gastric adenocarcinoma (AGS) cell line with stable knockdown of NET1." (PMID 21284875, 2011). "An in vitro model of stable knockdown of NET1 was achieved in AGS human gastric adenocarcinoma cells via lentiviral mediated transduction of short-hairpin (sh) RNA targeting NET1." (PMID 21284875, 2011). "In vitro studies have shown NET1 expression to drive invasion in gastric adenocarcinoma." (PMID 23945136, 2013).
gastric tumor (2 papers, 2008 to 2021). "In gastric tumor, NET1 has been shown to trigger cancer cell migration, invasion and cytoskeletal actin organization." (PMID 33839702, 2021). "We aimed to characterise the function of NET1 in the gastric tumour setting by defining the mechanism underpinning its effect in promoting tumour cell invasion." (PMID 18827818, 2008). "In this study, we demonstrate the activity of NET1 in driving cytoskeletal rearrangement, a key pathological mechanism in gastric tumour cell migration and invasion." (PMID 18827818, 2008). "We have shown that NET1 is a key player in LPA-induced activation of RhoA and the subsequent migration and invasion of gastric tumour cells." (PMID 18827818, 2008).
leukemia (2 papers, 2011 to 2022). A malignant (clonal) hematologic disorder, involving hematopoietic stem cells and characterized by the presence of primitive or atypical myeloid or lymphoid cells in the bone marrow and the blood. "Interestingly, Net1 colocalizes with these proteins in discrete punctate nuclear structures that are associated with promyelocytic leukemia (PML) bodies." (PMID 21390328, 2011).
aneuploidy (1 paper, 2024). Chromosomal disorder consisting of the presence a chromosomal abnormality in which there is an addition or loss of chromosomes within a set. "The high frequency of spindle/chromosomal defects in Net1-KD oocytes led us to assess whether aneuploidy was also associated with this defect." (PMID 38169395, 2024). "If these attachment errors are not corrected prior to anaphase in normal oocyte maturation, they may cause chromosome-separation defects; and consistent with this concept, the frequency of aneuploidy was significantly increased in Net1-depleted oocytes relative to controls." (PMID 38169395, 2024).
atherosclerosis (1 paper, 2022). A disease characterized by the build-up of fatty material and calcium deposition in the arterial wall resulting in partial or complete occlusion of the arterial lumen. "However, Net1 deletion may impair macrophage recruitment in the atherosclerosis mice model, which needs to be investigated." (PMID 35845072, 2022).
Barrett’s oesophagus (1 paper, 2013). "We aimed to investigate whether NET1 plays a functional role in oesophageal cancer (OAC) and its pre-malignant phenotype Barrett’s oesophagus." (PMID 23945136, 2013).
bladder tumor (1 paper, 2020). "It has been observed that the miR-22-3p enhanced resistance to chemotherapy in bladder tumor cells through suppressing NET1." (PMID 33183321, 2020). "NET1 was introduced as the direct target of miR-22-3p in chemo resistance of bladder tumor cells." (PMID 33183321, 2020).
colon cancer (1 paper, 2025). "Additionally, circ_0017552 was shown to enhance colon cancer cell proliferation through SP1-induced NET1 expression." (PMID 40652278, 2025).
COVID-19 (1 paper, 2024). A disease caused by infection with severe acute respiratory syndrome coronavirus 2. "All proteins were significantly different in COVID-19 patients from non-COVID-19 patients, while ProSAAS and NET1 were not significantly different between COVID-19 and healthy controls (FDR-adjusted P < 0.05)." (PMID 38760690, 2024). "When compared to healthy controls, 4 proteins out of the 28 (Galanin, ProSAAS, VimentinB, and NET1) were not significantly different from COVID-19 patients." (PMID 38760690, 2024).
epidermoid carcinoma (1 paper, 2014). "In addition, we designed shRNA and siRNAs against NET-1, and constructed them into vectors prior to transfected into an epidermoid carcinoma cell line (A431 cells) to identify the effects of NET-1 gene on A431 cells and the growth of transfected A431 cell xenograft in nude mice." (PMID 24196235, 2014).
liver cancer (1 paper, 2020). An epithelial or non-epithelial malignant neoplasm that arises from the liver. "Meanwhile, we also found that NET1 level in hepatic cancer cell line including Hep-G2, Huh7, SMMC-7721 and HL-7702 was significantly higher than that in normal HEK293T cells." (PMID 32641699, 2020). "In this study, we found NET1 regulated propofol-induced inhibitory effect on liver cancer cell invasion and migration." (PMID 32641699, 2020). "Meanwhile, the effect of NET1 silencing on SMMC-7721 migration was comparable with that in propofol-treated cells, showing that downregulation of NET1 led to impairment in hepatic cancer cell migration." (PMID 32641699, 2020).
lung adenocarcinoma (1 paper, 2020). A carcinoma that arises from the lung and is characterized by the presence of malignant glandular epithelial cells. "Our present work demonstrated that miR-22 had a relatively low expression, and NET1 had a relatively high expression in both NSCLC samples and lung adenocarcinoma cell lines compared with corresponding normal controls." (PMID 32420320, 2020).
neuroblastoma (1 paper, 2020). Neuroblastoma (NB) is the most common solid, extracranial childhood tumor. "Targeted radiotherapy with 131I-mIBG, a substrate of the human norepinephrine transporter (NET-1), shows promising responses in heavily pre-treated neuroblastoma (NB) patients." (PMID 33262374, 2020).
oesophageal adenocarcinoma (1 paper, 2013). "The putative role of NET1 in epithelial mesenchymal transition via TGF-β and the significance of this concept in OAC, coupled with the data presented here, strengthen the hypothesis that NET1 plays an important role in the tumour biology of oesophageal adenocarcinoma." (PMID 23945136, 2013).
oesophageal cancer (1 paper, 2013). "Because of this high NET1 level we chose this cell line for further experiments to characterise the role of NET1 in oesophageal cancer." (PMID 23945136, 2013).
osteosarcoma (1 paper, 2021). A usually aggressive malignant bone-forming mesenchymal neoplasm, predominantly affecting adolescents and young adults. "Thus, the NET-1 protein may be a potential therapeutic target of osteosarcoma." (PMID 34041269, 2021).
pancreatic cancer (1 paper, 2021). "A novel 14-gene signature comprising CCDC148, SH3RF2, CACNA1D, POLD3, PARP1, AP1M2, C4orf19, ANO1, VGLL1, SCEL, INPP4B, NET1, INSIG2 and BVES and a corresponding risk score formula were established for pancreatic cancer risk stratification and prognosis prediction." (PMID 33731794, 2021).
scoliosis (1 paper, 2025). A congenital or acquired spinal deformity characterized by lateral curvature of the spine. "In our study, we observed that HLA DR on CD14+ CD16+ monocyte was associated with a reduced risk of scoliosis, and SNHG14, SNORA33, and NET1 shared the same variant with HLA DR on CD14+ CD16+ monocyte." (PMID 40177401, 2025). "SNHG14, SNORA33, NET1, and SNORD100 shared the same variant with HLA DR on CD14+ CD16+ monocyte which could decrease the risk of scoliosis." (PMID 40177401, 2025).
skin carcinoma (1 paper, 2014). "Though investigating the expression and function of NET-1 gene, this study will provide a potential target to treat skin carcinoma." (PMID 24196235, 2014).
cancer (29 papers, 2005 to 2026). A tumor composed of atypical neoplastic, often pleomorphic cells that invade other tissues. "Net1 RNA encodes a guanine exchange factor and is strongly localized to neurites, the basal pole of intestinal epithelial cells, and to the projections of migrating cancer cells." (PMID 36867563, 2023). "Moreover, we observe that loss of Net1 reduces cancer cell proliferation, inhibits tumor angiogenesis, and promotes tumor cell apoptosis." (PMID 29769144, 2018). "Net1, a guanine nucleotide exchange factor, is one of the screened new genes and is particularly active in cancer cells and is involved in cell proliferation and differentiation." (PMID 39675772, 2025). "Many studies have demonstrated that Net1 is highly enriched in a variety of human cancers and that it facilitates cell proliferation, differentiation and invasion by regulating actin cytoskeleton rearrangement and mitosis." (PMID 39675772, 2025). "The modulation of the NET1 signalling pathway by small molecules targeting the GAG-binding site is a compelling strategy for the treatment of cancer and developmental disorders, and for stem cell therapies." (PMID 36869049, 2023). "In malignant tumors of digestive system, NET1 acts as a driver of tumor cell migration and invasion, an activity facilitated by regulating RhoA and cytoskeletal reorganization in gastric cancer." (PMID 32420320, 2020). "Here, using an inducible system of 3D collective invasion, we find that both RAB13 and NET1 RNAs are localized in invasive cancer spheroids." (PMID 33060293, 2020). "Protrusion-enriched RNAs encode factors linked to cancer progression, such as the RAB13 GTPase and the NET1 guanine nucleotide exchange factor, and are regulated by the tumor-suppressor protein APC." (PMID 33060293, 2020). "Collectively, these observations did not seem to be in favor of major role of the YAP/TAZ‐mediated signals in the response of cancer cells to the combined DAC/+net1‐mAB treatment." (PMID 27378792, 2016). "The NET1 gene has a key role in organization of the actin cytoskeleton and thus in the ability of cancer cells to migrate and invade." (PMID 24196235, 2014). "Expression of Beclin-1, PCNA, NET-1, Bcl-2, Bax, Survivin in cancer cells and CD34 in stromal microvessels were evaluated immunohistochemically in tissue microarrays comprising 103 cases of HCC and 57 matched adjacent nontumor liver tissues." (PMID 24885292, 2014). "NET-1 as a novel tumor relative gene is over-expressed in many malignant tumors including the breast, uterine cervix, colon, esophagus, liver, lung, ovary, pancreas, prostate, gastrointestinal, and skin." (PMID 24307893, 2013). "As these traits are vital to cellular proliferation in the cancer setting, these data support a role for NET1 as a suppressor of these pathways." (PMID 21284875, 2011). "Using β-actin mRNA expression to normalise, quantitative PCR confirmed elevated levels of Net1 expression in all cancer tissue specimens studied, in comparison with adjacent normal tissue." (PMID 16552434, 2006). "NET1 is a guanine nucleotide exchange factor specific for the small GTPase Rho and participates in diverse biological processes, including cytoskeletal dynamics, cancer and DNA damage." (PMID 38169395, 2024). "Neuroepithelial transforming gene 1 (Net1) is a RhoA subfamily-specific guanine nucleotide exchange factor that is involved in diverse biological processes, especially in mitotic progression, cell motility, and most malignant tumors." (PMID 38169395, 2024). "NET1 is a new member of the tetraspanins group and correlated with malignant tumor development." (PMID 32641699, 2020). "Moreover, miR-22 directly regulated NET1 and was verified to weaken cancer cell proliferation and migration, as well as enhance cell apoptosis by suppressing NET1." (PMID 32420320, 2020).